SLAMF1 (signaling lymphocytic activation molecule family member 1)
Diseases named in the same sentence as SLAMF1 in open-access papers (continued):
Sharing a sentence is not in itself a finding about the gene and the disease.
colon cancer (3 papers, 2018 to 2024). "Transfection of CD3-activated T-cells with SLAMF1 increased their cytotoxic activity and IFNγ production in vitro against human colon cancer cells." (PMID 38476238, 2024). "Intriguingly, SLAMF1 is a potential predictive biomarker for colon cancer since the SLAMF1high group of colon cancer patients had a better overall survival compared to the SLAMF1low group." (PMID 36189323, 2022). "In xenograft models, these T cells reduced tumor growth, suggesting increased SLAMF1 expression on T cells in colon cancer may be beneficial." (PMID 38476238, 2024). "Notably, the authors identified the signaling lymphocytic activation molecule family member 1 (SLAMF1), a surface protein which was specifically and highly expressed in tumor ILCs (mainly ILC1-like and ILC2) and to a lower level in the blood of colon cancer patients but absent in the normal blood." (PMID 36189323, 2022).
X-linked lymphoproliferative disease (3 papers, 2014 to 2022). X-linked lymphoproliferative disease is a hereditary immunodeficiency characterized, in the majority of cases, by an inadequate immune response to infection with the Epstein-Barr virus (EBV). "However, only development of iNKT cells, but not other hematopoietic cells, is absent in patients with X-linked lymphoproliferative disease (SAP defect) and SAP-deficient mice or reduced in NOD, SLAMF1/SLAMF6 double mutant chimeras and in Fyn deficient mice." (PMID 25142143, 2014).
acute myocardial infarction (2 papers, 2020 to 2022). Necrosis of the myocardium, as a result of interruption of the blood supply to the area. "In addition, compared with the healthy control group, SLAMF1 was significantly down-regulated in patients with acute myocardial infarction (AMI)." (PMID 32746852, 2020).
atopic dermatitis (2 papers, 2025). "In summary, this study identified a SLAMF1:c799 + 2 T > C splice donor variant associated with allergic dermatitis in domestic dogs." (PMID 40612147, 2025). "In this study, a SLAMF1 splice donor variant (SLAMF1:c799 + 2 T > C) associated with allergic dermatitis was identified through GWAS analysis, followed by whole-genome resequencing." (PMID 40612147, 2025). "The identification of the SLAMF1:c799 + 2 T > C variant also presents an opportunity for breeders to breed dogs with a lower risk of developing atopic dermatitis." (PMID 40612147, 2025). "Further analysis of additional genome sequences and RNA samples from the MARS PETCARE BIOBANK confirmed that the SLAMF1 splice variant is a strong potential contributor to an increased risk of atopic dermatitis." (PMID 40612147, 2025). "There may be a possibility that SLAMF1:c799 + 2 T > C has a dual effect— increasing both the risk of an initial presentation of atopic dermatitis and the development of secondary yeast infections." (PMID 40612147, 2025). "In addition to the SLAMF1 variant identified, significant associations were also established between atopic dermatitis and the dog leukocyte antigen (DLA) region." (PMID 40612147, 2025). "Although no direct link has been established between SLAMF1 and atopic dermatitis, there is reasonable evidence suggesting that SLAMF1 is involved in related disease processes." (PMID 40612147, 2025).
autoimmune thyroid disease (2 papers, 2020). Inflammatory disease of the thyroid gland due to autoimmune responses leading to lymphocytic infiltration of the gland. "Expression of SLAMF1 was significantly increased in peripheral blood CD4+, T helper 17, and CD19+ B cells from autoimmune thyroid disease patients." (PMID 32746852, 2020).
Burkitt lymphoma (2 papers, 2017 to 2024). A rare form of malignant mature B-cell non-Hodgkin lymphoma. "Here, it should be noted that the expression of SLAMF1/CD150 in Burkitt lymphoma could depend on the presence of Epstein–Barr virus infection." (PMID 38612827, 2024). "The Burkitt lymphoma cell lines Raji, Namalwa 12 (EBV+), and BJAB (EBV−) expressed SLAMF1/CD150 at a moderate level; all other B cell lines tested (REH, Ramos, B104, and RPMI-8226) were SLAMF1/CD150 negative." (PMID 38612827, 2024). "Another flow cytometry study showed that SLAMF1/CD150 was partially positive in the Namalwa (40–60% cells positive), Raji (60–80%), and Ramos (20–40%) Burkitt lymphoma cell lines and negative only in Daudi (<20%) Burkitt lymphoma B cells." (PMID 38612827, 2024).
Chagas disease (2 papers, 2012 to 2024). A parasitic infection caused by Trypanosoma cruzi. "Our study points to IFI204/IFI16 and BST2 as potential Chagas disease targets and SLAMF1 as their inhibitor through some unknown mechanism." (PMID 39000601, 2024). "Consequently, Slamf1 is a key molecule in T. cruzi infectivity and represents an attractive novel therapeutic target for modulating T. cruzi infection and Chagas' disease." (PMID 22807679, 2012).
Cirrhosis (2 papers, 2021 to 2022). A chronic disorder of the liver in which liver tissue becomes scarred and is partially replaced by regenerative nodules and fibrotic tissue resulting in loss of liver function. "In accordance with HBV mediated inflammation, we found elevated levels of IL-8 and SLAMF1 to be associated with the development of clinical cirrhosis." (PMID 34782638, 2021). "Among those with low HBV viral levels at baseline (< 45,920 copies/mL) only the associations between HGF, SLAMF1, uPA, and cirrhosis were found to be statistically significant." (PMID 34782638, 2021). "In another study, the concentration of SLAMF1 has a profound effect on the formation of cirrhosis in the plasma." (PMID 36281288, 2022). "HGF, SLAMF1, CSF1, and uPA were associated with cirrhosis among those diagnosed ≥ 6.57 years after serum collection." (PMID 34782638, 2021).
colitis (2 papers, 2012 to 2016). Inflammation of the colon. "The production of pro-inflammatory cytokines that are implicated in colitis development are also impaired by SLAMF1-deficiency." (PMID 26834746, 2016). "SLAMF1 expression is induced by stimulation with either LPS or IL-1β and in phagocytes during active colitis." (PMID 26834746, 2016). "SLAMF1 in phagocytes also contributes to the development of colitis." (PMID 26834746, 2016). "By adoptive transfer of CD45RBhi CD4+ T-cells into Rag−/− or SLAMF1−/−Rag−/− mice, we found that only SLAMF1 expression by innate cells, and not T-cells, is required for the full induction of experimental colitis." (PMID 26834746, 2016).
diabetes (2 papers, 2024 to 2025). "Similarly, we also identified many metabolites and several proteins (e.g., SLAMF1: signaling lymphocytic activation molecule and IL-15RA: interleukin-15 receptor subunit alpha) associated with HIV infection and diabetes in the same direction." (PMID 38643166, 2024).
glioma (2 papers, 2015 to 2023). A benign or malignant brain and spinal cord tumor that arises from glial cells (astrocytes, oligodendrocytes, ependymal cells). "A paper has reported that the nSLAMF1 isoform is the main SLAMF1 isoform in glioma cells and suggested that SLAMF1 expression in the central nervous system (CNS) tumors can serve as a new diagnostic marker as well as a potential target for innovative therapeutic approaches in the future." (PMID 37251372, 2023).
Hodgkins lymphoma (2 papers, 2017 to 2018). A heterogeneous group of malignant lymphoid neoplasms of B-cell origin characterized histologically by the presence of Hodgkin and Reed-Sternberg (HRS) cells in the vast majority of cases. "In this scenario, interaction of SLAMF1 expressed on infiltrating T cells with SLAMF1 of Hodgkin’s lymphoma cells inhibits cell proliferation and induces apoptosis in L1236 Hodgkin’s lymphoma cells independent of JNK activity." (PMID 29662641, 2018). "Because, SLAMF1 regulates phosphorylation of MAPKs Erk1/2 and p38, it has been proposed that it can contribute to the regulation of tumor cell maintenance in low-rate proliferating Hodgkin’s lymphoma cells." (PMID 29662641, 2018). "SLAMF1-mediated phosphorylation of Akt activates the phosphorylation of its downstream targets (GSK-3β and FoxO1) in EBV-transformed and Hodgkin›s lymphoma cells." (PMID 29662641, 2018).
lymphoma (2 papers, 2016 to 2023). A malignant (clonal) proliferation of B- lymphocytes or T- lymphocytes which involves the lymph nodes, bone marrow and/or extranodal sites. "Finally, the observations that SLAMF1 is found on lymphomas and that Nectin-4 is expressed on the cell surfaces of many adenocarcinomas highlight the potential of measles virus for oncolytic therapy." (PMID 27657109, 2016). "However, the panel targeted the most relevant genes for lymphoma diagnosis but did not cover all exons for some genes (e.g., KMT2D) and lacked a few select genes (e.g., FAS, SLAMF1, SPEN, and NCOR2), which are described in cutaneous MZL10,32." (PMID 37081015, 2023).
mantle cell lymphoma (2 papers, 2017 to 2024). Mantle cell lymphoma is a rare form of malignant non-Hodgkin lymphoma affecting B lymphocytes in the lymph nodes in a region called the ``mantle zone''. "Two out of two cases of mantle cell lymphoma (MCL) displayed low levels of SLAMF1/CD150 expression." (PMID 38612827, 2024).
ovarian carcinoma (2 papers, 2021 to 2024). A malignant neoplasm originating from the surface ovarian epithelium. "Moreover, LY9 and SLAMF1 were identified as the real hub genes associated with the overall survival of ovarian cancer patients by affecting the infiltration of activated B cells." (PMID 34461858, 2021). "Finally, LY9 and SLAMF1 were recognized as the real hub genes in immune infiltrates of ovarian cancer." (PMID 34461858, 2021). "Thus, the expression of LY9 and SLAMF1 was higher in ovarian cancer tissues than in normal ovarian tissues, and the high expression of these 2 genes was relevant to the prognosis of ovarian cancer." (PMID 34461858, 2021). "LY9 and SLAMF1 might be potential therapeutic targets of ovarian cancer." (PMID 34461858, 2021).
parasitemia (2 papers, 2012 to 2020). "Parasitemia was lower in Slamf1-/- than in BALB/c mice for Y and VFRA strains, despite VFRA being more infective in SLAMF1 deficient macrophages." (PMID 32925918, 2020). "BALB/c and Slamf1-/- mice infected with the Y strain presented the first peak of parasitemia at 9 dpi, and with VFRA it was delayed to 14–16 dpi." (PMID 32925918, 2020). "By contrast, the number of parasites in the blood followed similar kinetics in both mouse strains, although parasitemia was slightly lower than in Slamf1−/− mice than in Slamf1+/+ BALB/c mice." (PMID 22807679, 2012). "Moreover, a recent study shows that Nox2 inhibition ameliorates T. cruzi-induced myocarditis independently of parasitemia levels as in Slamf1−/− mice." (PMID 22807679, 2012). "Cardiac damage was reduced in Slamf1−/− mice compared to wild type mice, infected with the same doses of parasites, as a result of a decrease of the number of parasites in the heart even the parasitemia was only marginally less." (PMID 22807679, 2012). "Notably, Slamf1-/- mice showed lower parasitemia than BALB/c mice with both parasite strains." (PMID 32925918, 2020). "As in the Slamf1−/− mouse the monoclonal antibody directed against Slamf1 did not affect the parasitemia in the blood (data not shown)." (PMID 22807679, 2012). "Since Slamf1 is only expressed in myeloid cells, the replication of T. cruzi in non-hematopoietic cells is not likely to be impaired in Slamf1−/− mice and hence the blood-borne parasitemia is only slightly less in the mutant mice." (PMID 22807679, 2012). "This explains why T. cruzi infected Slamf1−/− mice do not succumb to myocarditis induced by a lethal challenge with the highly virulent T. cruzi Y strain quite the opposite to BALB/c mice even with similar parasitemia levels." (PMID 22807679, 2012).
prostate carcinoma (2 papers, 2023 to 2024). A carcinoma that arises from epithelial cells of the prostate gland. "Whether the expression of SLAMF1 is associated with clinical outcomes in prostate cancer remains to be determined." (PMID 38476238, 2024). "SLAMF1 cell surface and cytoplasmic expression have been detected in the prostate cancer cell lines LNCap, Du-145, and PC-3." (PMID 38476238, 2024).
subacute sclerosing panencephalitis (2 papers, 2021 to 2025). A chronic progressive encephalitis that develops a few years after measles infection and presents with a demyelination of the cerebral cortex. "MeV may persist in the brain, which does not express SLAMF1 and nectin-4, leading to subacute sclerosing panencephalitis (SSPE) several years after acute infection." (PMID 40192292, 2025).
Bell's palsy (1 paper, 2025). Partial or complete paralysis of the facial muscles of one side of a person's face. "Conversely, Signaling Lymphocytic Activation Molecule Family Member 1 (SLAMF1) is a protective factor for Bell's palsy and a risk factor for inflammatory bowel disease." (PMID 40760834, 2025). "CXCL5, IL_17C, and SLAMF1 are possible co‐acting pathways between Bell's palsy and inflammatory bowel disease." (PMID 40760834, 2025).
brucellosis (1 paper, 2025). Brucellosis is a bacterial infection that spreads from animals to people via unpasteurized dairy products or by exposure to contaminated animal products or infected animals. "Several genes of the SLAM family (SLAMF1, SLAMF7, and SLAMF8) were overexpressed in acute but not in chronic brucellosis patients, unlike stable TLR9 gene expression." (PMID 40231463, 2025).
cardiac hypertrophy (1 paper, 2020). "Cardiac hypertrophy was only observed at the LA phase, where BALB/c and Slamf1-/- mice infected with the Y strain showed higher cardiac hypertrophy compared to VFRA." (PMID 32925918, 2020).
cervical cancer (1 paper, 2021). A primary or metastatic malignant neoplasm involving the cervix. "Previous studies have shown that the expressions of SLAMF1 in cervical cancer and SLAMF6 in liver cancer were closely related to tumor infiltration of immune cells and patient prognosis." (PMID 34733790, 2021).
facial paralysis (1 paper, 2025). Severe or complete loss of facial muscle motor function. "This study also suggests that CXCL5 and SLAMF1 may act as common pathways of action between facial paralysis and IBD etiology, possibly through mechanisms that regulate immune responses, promote tissue repair, and maintain immune homeostasis." (PMID 40760834, 2025).
fungal infections (1 paper, 2025). "A Study on a SLAMF1−/− TCR knockout mice showed that SLAMF1 is required for resistance to environmental fungal infections." (PMID 40612147, 2025).
Hepatomegaly (1 paper, 2020). Abnormally increased size of the liver. "Hepatomegaly was also induced by infection with the two parasite strains in both strains of mice and it was significantly higher in BALB/c compared to Slamf1-/- in mice infected with Dm28 and VFRA." (PMID 32925918, 2020).
HIV-1 infection (1 paper, 2023). The type species of lentivirus and the etiologic agent of acquired immunodeficiency syndrome (AIDS). "SLAMF1, also known as CD150, plays an important role in immunosuppression of HIV-1 infection." (PMID 36408648, 2023).
ischemic stroke (1 paper, 2020). A stroke disorder caused by obstruction of blood flow to the brain, due to thrombotic (local blood clot formation) or embolic (due to a blood clot or other material traveling from another site) event. "In this study, we found that SLAMF1 was downregulated in the IS patient samples which indicate that SLAMF1 may be a potential target for medical intervention in patients with ischemic stroke." (PMID 32746852, 2020). "In the present study, we investigated the immune related gene expression modules, in which the SLAMF1, IL7R and NCF4 may be novel therapeutic targets to promote functional and histological recovery after ischemic stroke." (PMID 32746852, 2020). "However, the dysfunction of SLAMF1 in ischemic stroke has not been reported before." (PMID 32746852, 2020).
myasthenia gravis (1 paper, 2017). Myasthenia gravis (MG) is a rare, clinically heterogeneous, autoimmune disorder of the neuromuscular junction characterized by fatigable weakness of voluntary muscles. "Thus, the minor variant of the rs3753381 polymorphism may contribute to the development of myasthenia gravis by modulating SLAMF1 expression, presumably in pathogenic B-lymphocytes." (PMID 29104781, 2017).
myocarditis (1 paper, 2012). Myocarditis is a condition that is characterized by inflammation of the heart muscle (myocardium). "This explains why T. cruzi-infected Slamf1 deficient mice do not succumb to myocarditis induced by a lethal challenge with T. cruzi in contrast to BALB/c mice." (PMID 22807679, 2012).
Obesity (1 paper, 2018). Accumulation of substantial excess body fat. "Interestingly, all tissues of T2D patients showed altered expression of genes involved in the inflammation response—such as SOCS1 in WB; CCL20 and SLAMF1 in SAT; ACP5, FOS, and JUN in VAT; and PLA2G2A in LT, showing the relevance of the systemic chronic inflammation in obesity and T2D." (PMID 29466957, 2018).
peritonitis (1 paper, 2015). Inflammation of the peritoneum (tissue that lines the abdominal wall and covers most of the organs in the abdomen). "In support of this notion are our observations that infiltration of Slamf1-/- macrophages and monocytes to the sites of inflammation is markedly reduced in two models of enterocolitis and in peritonitis." (PMID 25799045, 2015). "The total number of cells in the peritoneal cavity of Slamf1-/-Balb/c mice was lower than the number of cells in wt Balb/c mice four days after induction of peritonitis." (PMID 25799045, 2015).
rectum cancer (1 paper, 2022). "Low SLAMF1 expression was associated with poor survival in CRC and rectum cancer which identified SLAMF1 as a potential biomarker and SLAMF1+ ILCs as a population with anti-tumor effect." (PMID 35663967, 2022).
Stroke (1 paper, 2020). Sudden impairment of blood flow to a part of the brain due to occlusion or rupture of an artery to the brain. "The proportion of neutrophil distributed in the peripheral blood of stroke patients increased, in which the gene expression of IL7R, SLAMF1 and CCR7 were low, and vice versa." (PMID 32746852, 2020).